KRTAP12-2 (keratin associated protein 12-2)
Description:
In the hair cortex, hair keratin intermediate filaments are embedded in an interfilamentous matrix, consisting of hair keratin-associated proteins (KRTAP), which are essential for the formation of a rigid and resistant hair shaft through their extensive disulfide bond cross-linking with abundant cysteine residues of hair keratins. The matrix proteins include the high-sulfur and high-glycine-tyrosine keratins.
Synonyms: KAP12.2; KRTAP12.2
Tractability: No criterion of Open Targets' tractability assessment is met for any kind of drug.
Gene: Protein-coding gene on chromosome 21 (44,666,189 to 44,666,927, reverse strand). Ensembl gene ENSG00000221864.
Pathways (Reactome):
Developmental Biology: Keratinization
Gene Ontology:
Molecular function: protein binding
Cellular component: cytosol
Genetic constraint (gnomAD): Loss-of-function variants: 1 observed, 1.28 expected, observed/expected ratio (o/e) 0.78, 90% interval 0.23 to 1.86. That is too few expected variants to judge how well the gene tolerates losing a copy. Missense variants: 165 observed, 182.5 expected, observed/expected ratio (o/e) 0.9, 90% interval 0.8 to 1.03. Synonymous variants: 73 observed, 84.09 expected, observed/expected ratio (o/e) 0.87, 90% interval 0.72 to 1.05.
Homologues: Orthologues: rat Krtap10-1 (41% identical), rat LOC120098854 (40% identical), rat Krtap10-9 (38% identical), mouse Gm49918 (34% identical), mouse Krtap10-29 (34% identical), mouse Krtap10-31 (34% identical), rat Krtap10-1l1 (34% identical), mouse Krtap10-21 (34% identical), mouse Krtap10-22 (34% identical), mouse Krtap10-25 (34% identical), mouse Krtap10-26 (34% identical), mouse Krtap10-27 (34% identical), and 13 more. Paralogues in human: KRTAP12-1 (59% identical), KRTAP12-3 (46% identical), KRTAP10-9 (42% identical), KRTAP10-4 (41% identical), KRTAP10-11 (40% identical), KRTAP16-1 (40% identical), KRTAP10-2 (39% identical), KRTAP10-7 (39% identical), KRTAP10-5 (38% identical), KRTAP10-12 (34% identical), KRTAP10-6 (34% identical), KRTAP10-10 (33% identical), and 35 more.